AR (androgen receptor)
Diseases named in the same sentence as AR in open-access papers (continued):
Sharing a sentence is not in itself a finding about the gene and the disease.
hypospadias (continued). "Data from the literature indicate that between 10–30% of human hypospadias cases can be at-tributed to specific gene mutations (e.g., AR gene mutation, SRD5A type II deficiency), while 70% of cases have unknown etiology, possibly a combination of genes and environmental factors." (PMID 37238140, 2023). "Moreover, not only are their mutations reported in the coding region of AR, but also SNPs located in the promoter region of AR gene were involved in the development and severity of hypospadias however, the functional importance of these mutations remains less known." (PMID 34276780, 2021). "Furthermore, our genetic results identified a rare damaging AR allele (p.Arg841His) and other hypospadias risk mutants in all three hypospadias patients suggesting that compound variants might contribute to the genetic etiology of hypospadias in this family." (PMID 32515122, 2020). "Mutations in AR transcriptional regulators, promoter hypermethylation, and chromatin accessibility differences provide plausible explanations for lower AR expression in hypospadias patients." (PMID 41596366, 2026). "Additional studies report differential DNA methylation at AR pathway loci and altered chromatin accessibility in urethral or foreskin tissue from hypospadias compared with controls." (PMID 41596366, 2026). "Skinner’s group reports genome-wide differentially methylated regions (DMRs) in human penile foreskin from hypospadias, including DMRs at AR pathway loci and transgenerational epimutations after gestational vinclozolin exposure in mice." (PMID 41596366, 2026). "Epigenetic repression of AR, including promoter hypermethylation, has been directly demonstrated in hypospadias foreskin, implicating reduced AR expression in hypospadias." (PMID 41596366, 2026). "With these controlled conditions, perhaps the role of AR in hypospadias pathogenesis can truly be uncovered." (PMID 41596366, 2026). "These inconsistencies underscore the complexity of AR regulation in hypospadias and suggest the need for investigation into the role of AR expression in the pathophysiology of hypospadias." (PMID 41596366, 2026). "Prior work has compared AR expression between hypospadias and control tissues with mixed findings, likely reflecting differences in age at surgery, sampling site, severity, preoperative hormones, and assay protocols." (PMID 41596366, 2026). "Epigenetic findings do connect EDC exposure to AR pathway modulation in hypospadias, showing AR promoter hypermethylation with reduced AR expression in hypospadias foreskin." (PMID 41596366, 2026). "These limitations define the minimal reporting and design standards needed for future studies capable of resolving AR pathway involvement in hypospadias pathogenesis." (PMID 41596366, 2026). "In some studies, 100% of mice exposed to vinclozolin during the critical window of urethral closure developed hypospadias, with the affected mice having significantly lower expression of AR protein." (PMID 41596366, 2026). "To determine if there is a significant difference in AR expression of hypospadias, we conducted a random-effects meta-analysis on the mRNA studies." (PMID 41596366, 2026). "To clarify how the androgen receptor contributes to human hypospadias, we conducted a quantitative meta-analysis comparing androgen receptor expression in hypospadias patients and healthy boys." (PMID 41596366, 2026). "Of those, two studies reported an increase in AR expression in hypospadias, while four studies reported decreased expression." (PMID 41596366, 2026). "Little is known about AR-relevant genomic alterations within the non-coding regions of patients with hypospadias." (PMID 41596366, 2026). "Studies of such patients described mutations in other genes crucial for sexual development, such as the hypospadias-associated MAMLD1 gene or the FKBP4 gene, encoding a regulator of the AR signaling pathway." (PMID 40247401, 2025).
hypospadias (continued). "For instance, AR CAG repeat length was significantly greater in 44 boys with isolated hypospadias compared to 79 controls (mean: 24.4 ± 2.8 vs. 22.7 ± 3.3; p < 0.05)." (PMID 41595460, 2025). "Fetal exposure to various anti-androgenic chemicals induces genital malformations, such as hypospadias, in male rodents, as also demonstrated in this study with the AR antagonist flutamide." (PMID 41019341, 2025). "Significantly reduced AR expression was observed in hypospadias patients vs. controls [average optical density (AOD), 0.38 ± 0.09 vs. 0.56 ± 0.11]." (PMID 40948500, 2025). "To have a model of hypospadias, we utilized the potent AR antagonist and pharmaceutical flutamide, which has previously been used as a model chemical to induce hypospadias in rats." (PMID 41019341, 2025). "Understanding the molecular mechanisms linking an EDC stressor event, such as AR antagonism, to hypospadias - including its influence on other hormone pathways - can help delineate the causal toxicity pathways for EDC-induced hypospadias." (PMID 41019341, 2025). "Of note, previous studies have indicated that patients with severe hypospadias exhibit a defect in the AR gene." (PMID 39624466, 2025). "We conducted a large prospective study to clarify discrepancies in AR expression between hypospadias patients and normal children, and to assess the relationship between AR dysregulation and hypospadias development." (PMID 40948500, 2025). "Our study demonstrated that AR expression is significantly decreased in patients with hypospadias than in healthy boys." (PMID 40948500, 2025). "Polymorphic CAG repeats in exon 1 of the AR gene inversely affects receptor transactivation; longer CAG repeats reduce AR activity and were associated with reduced fertility and hypospadias in multiple studies." (PMID 41595460, 2025). "Gene mutations in androgen receptor (AR), 5-α reductase (SRD5A2), and steroidogenic factor 1 (NR5A1) are linked to hypospadias formation." (PMID 39642224, 2024). "Compared to normal offspring, hypospadias rats exhibited decreased serum testosterone levels and reduced AR expression in the GT." (PMID 39698037, 2024). "There were also decreases in the expressions of the enzymes Cyp11a1, Hsd3b, Scarb1 and Star, and the expressions of AR and Srd5a2 were decreased only in the testes of rats with hypospadias." (PMID 39728417, 2024). "Among the Chinese population, SRD5A2 and AR dysfunction have been discovered in some patients with hypospadias." (PMID 34276780, 2021). "One de novo missense mutation loci was identified in AR and further in vivo and in vitro functional studies provided the molecular evidence that p.I817N amino acid change could cause significant reduction in AR transcriptional function which led to hypospadias." (PMID 34276780, 2021). "The steroid 5α-reductase 2 (SRD5A2) and androgen receptor (AR) genes are two androgen dependent genes that were widely evaluated in hypospadias." (PMID 34276780, 2021). "It was also noted that 11 mutations in SRD5A2 gene, 6 mutations in AR gene, and one variant in MID1 gene in this study were also correlated to abnormal male genital development and hypospadias." (PMID 34276780, 2021). "This points at a possible relationship between androgen receptor regulation being involved in the embryology of hypospadias and the functioning of the specific immune system – including LCs." (PMID 31718599, 2019). "The expression level of SRD5A2 mRNA in the hypospadias group was similar to that in the phimosis group; however, the AR mRNA expression level in the phimosis group was found to be higher than that in the hypospadias." (PMID 29080015, 2018). "A significantly higher CYP1B1 expression level and a lower AR expression level were observed in the hypospadias groups than in the phimosis group." (PMID 29080015, 2018).
hypospadias (continued). "Hypospadias and cryptorchidism are both related to androgen receptor function, and the role of fetal androgens is especially important during the first trimester, when organogenesis takes place." (PMID 26307850, 2016). "Impaired signaling through the androgen receptor (AR) leads to failure of urethral fold formation and fusion and consequently leads to hypospadias." (PMID 24799883, 2014). "In addition, in another study on Chilean population, the CAG and GGN polymorphisms in the AR gene has been investigated and showed that in isolated hypospadic boys, there are longer CAG alleles in their AR gene that might be associated with the development of hypospadias." (PMID 24799883, 2014). "Without the presence of adequate levels of testosterone or a functioning androgen receptor, the genital structures become female in appearance, as seen in the most severe cases of hypospadias." (PMID 23272655, 2012). "In the present study, we aimed at investigating the role of the CAG repeat length in the AR gene in hypospadias cases as compared to the controls." (PMID 23167717, 2012). "We compared the number of CAG repeats in the AR gene in each case from the hypospadias group with the repeats in individuals from the control group." (PMID 23167717, 2012). "In the present investigation, we detected a significantly expanded CAG repeat length located in exon 1 of the AR gene in the largest number of examined Caucasian patients with hypospadias reported so far." (PMID 23167717, 2012). "We have investigated the largest number of hypospadias cases with regards to the CAG repeat length, and we provide evidence that a higher number of the CAG repeat sequence in the AR gene have a clear effect on the risk of hypospadias in Caucasians." (PMID 23167717, 2012). "To quantitatively determine whether the protein levels of AR are higher in hypospadias patients, we conducted a random-effects meta-analysis on all the studies that reported protein data." (PMID 41596366, 2026). "Notably, AR protein and mRNA levels in these mutants remain comparable to the wild type, illustrating that hypospadias can arise from disruption of androgen-responsive downstream effectors, even when AR expression is unphased." (PMID 41596366, 2026). "Most studies investigating the impacts of AR expression in EDC-induced hypospadias are preclinical." (PMID 41596366, 2026). "Among these factors, AR signaling is a central factor in hypospadias pathogenesis." (PMID 41596366, 2026). "Clarifying the timing, regulation, and downstream effects of AR-mediated pathways in hypospadias may explain the heterogeneous clinical presentation and outcomes, allowing further opportunities for prevention and targeted intervention." (PMID 41596366, 2026). "This could further support that AR pathway disturbance in hypospadias is multifactorial, arising from genetic, epigenetic, and environmental mechanisms." (PMID 41596366, 2026). "In conclusion, the inner plate preputial tissues of patients with hypospadias showed decreased AR expression, suggesting that AR may be involved in hypospadias development and contributes to resolving a key controversy." (PMID 40948500, 2025). "Specifically, there is evidence suggesting that a crucially reduced level of AR mRNA expression could play a significant role in the development of hypospadias at the midshaft." (PMID 39624466, 2025). "Furthermore, AR expression was lower in the hypospadias group than in the control group (AOD, 0.38 ± 0.09 vs. 0.56 ± 0.11, P = 0.01)." (PMID 40948500, 2025). "Our findings contrast with prior reports of AR overexpression in hypospadias." (PMID 40948500, 2025). "Therefore, miR-143-3p can be another potential regulator of AR signaling, resulting in the regulation of hypospadias development." (PMID 39624466, 2025). "Notably, it should be considered that their study did not explore the detailed mechanism or the direct connection between AR signaling and the progression of hypospadias." (PMID 39624466, 2025).
hypospadias (continued). "AR expression in the inner plate of prepuce in hypospadias vs. control groups." (PMID 40948500, 2025). "However, abnormal expression, subcellular localization or function of AR can also contribute to hypospadias occurrence." (PMID 39318621, 2024). "CNV in KCTD13 has been identified to influence androgen receptor function via its changes in gene dosage, which might contribute to hypospadias." (PMID 39318621, 2024). "The same degree of hypospadias severity was shown to be true for AR knockouts at E14.5 and E17.5." (PMID 35846302, 2022). "Two of three hypospadias cases had pathogenic variants in SRD5A2 (case 51) and AR (case 94)." (PMID 34367232, 2021). "In conclusion, our study demonstrated that disrupted AR and CYP19A1 expression could play a causative role in the development of hypospadias." (PMID 32515122, 2020). "Although genetic research in AR has been investigated for association with the risk of hypospadias, the genetic contribution of AR gene to the risk of hypospadias is not clear." (PMID 32515122, 2020). "In addition, AR protein expression was found at higher levels in preputial tissue from subjects with severe hypospadias than those with mild hypospadias and control subjects." (PMID 32391298, 2020). "While any defect in the androgen signaling may lead to hypospadias, the AR expression in hypospadias are controversial with the variable results." (PMID 32515122, 2020). "Additionally, the expression level of AR mRNA was found to be lower in the hypospadias group than in the phimosis group." (PMID 29080015, 2018). "Co-regulators of the androgen receptor start being acknowledged as possible candidates for hormone-resistance instances, which could account for hypospadias." (PMID 17343741, 2007). "Variants in the AR gene, such as CAG and GGN repeat polymorphisms, and in the 5-α reductase 2 gene (SRD5A2), which converts testosterone (T) to the more potent dihydrotestosterone (DHT) have been associated with hypospadias." (PMID 17343741, 2007). "Androgen receptor defects have been shown to result in varying degrees of impaired masculinisation in XY individuals; however this is thought to be infrequent in hypospadias." (PMID 17343741, 2007). "Because AR expression varies across different developmental stages, especially during mini-puberty, studies that combine samples across these stages may obscure statistically significant differences between hypospadias and control." (PMID 41596366, 2026). "Due to substantial heterogeneity and imprecision in both mRNA and protein assays, no consistent direction of androgen receptor expression could be demonstrated, suggesting that hypospadias etiology may be more complicated than just the sole expression of the androgen receptor." (PMID 41596366, 2026). "Impaired AR transcriptional activity in hypospadias may be ameliorated by androgen supplementation." (PMID 40948500, 2025). "Hence, the expression of AR in patients with hypospadias remains controversial." (PMID 40948500, 2025). "Our null finding regarding AR expression across proximal/distal subtypes suggests that baseline AR deficiency may be a universal feature in hypospadias irrespective of severity." (PMID 40948500, 2025). "Interestingly, most patients in our cohort carrying AR variants exhibited no additional signs of androgen insensitivity beyond hypospadias and micropenis." (PMID 39285472, 2024). "AR and ER signaling could play a crucial role in the development of hypospadias." (PMID 32515122, 2020). "However, no mutation was detected in either AR or SRD5A2 in the third KS patient with scrotal hypospadias." (PMID 29022558, 2018). "Of the 29 cases who had an AR mutation, 20 had hypospadias at initial presentation and six (33%) continued to have a hypospadias despite surgical repair, whereas only one of the 20 with hypospadias and no AR mutation continued to have a hypospadias." (PMID 27403927, 2016). "In the 20 patients with severe hypospadias, no AR mutations were found." (PMID 22253624, 2012).
hypospadias (continued). "In none of the patients classified as severe (penoscrotal) hypospadias, an AR mutation was found." (PMID 22253624, 2012). "Additionally, epigenetic alterations can be involved in hypospadias development such as the methylation of the AR gene, the SRD5A2 gene, or CpG sites, determining the use of DNA methylation patterns to identify and evaluate new candidate genes that may be involved in the etiology of hypospadias." (PMID 37238140, 2023). "Our findings suggest that AR and ESR1 signaling play a critical role in the development of mild and severe hypospadias using the gene expression profiling." (PMID 32515122, 2020). "Compound rare damaging mutants of AR gene with HSD3B1 and SLC25A5 genes were identified in the different severe hypospadias." (PMID 32515122, 2020). "Since AR mediates important biological effect of testosterone and DHT, it is an obvious candidate in the development of hypospadias." (PMID 23167717, 2012). "Some studies have found increased levels of maternal anti-androgenic phthalates or pesticide exposure among mothers of boys with hypospadias, but direct pairing of concentration of exposure biomarkers with penile tissue AR quantification is lacking." (PMID 41596366, 2026). "In this systematic review and meta-analysis of human hypospadias studies, we found no consistent direction of effect in AR expression between hypospadias patients and controls, likely due to imprecision and highly heterogeneous results." (PMID 41596366, 2026). "Since these genes are not involved in the androgen signaling cascade, we expect minimal or no change in AR expression despite the presence of hypospadias." (PMID 41596366, 2026). "The current human literature does not support a uniform increase or decrease in AR expression in hypospadias tissue." (PMID 41596366, 2026). "Significant alterations in DNA methylation of sex hormone receptor genes (ESR1 and AR) and fibroblast growth factor (FGFR2 FGF8) may correlate with abnormal expression of these genes in patients with hypospadias." (PMID 39959693, 2025). "Reduced AR in basal cells may disrupt EMT, impairing urethral tubularization, resulting in failed urethral fusion and contributing to hypospadias pathogenesis." (PMID 40948500, 2025). "Our study demonstrated significantly reduced AR expression in hypospadias patients compared to healthy controls, with no differential expression between proximal and distal subtypes." (PMID 40948500, 2025). "In conclusion, our findings demonstrated that dysregulation of AR and CYP19A1 could play a crucial role in the development of hypospadias." (PMID 32515122, 2020). "AR and CYP19A1 were significantly decreased in severe and mild hypospadias." (PMID 32515122, 2020). "Our study provided preliminary evidence that the imbalance of AR and ESR1 signaling are present in hypospadias, which may affect the individual patient by various routes." (PMID 32515122, 2020). "Polymorphisms, mutations, and epigenetic changes in the AR, CYR61, HSD17B3, HSD3B1, MAMLD1, SRD5A2, and STARD3 have been associated to hypospadias risk in severe types of hypospadias that have not been found in mild hypospadias." (PMID 33425810, 2020). "In addition, SNP rs5919436 in the AR gene was found to have a significant association with Type III hypospadias, but not for Type I and Type II hypospadias." (PMID 33312738, 2020). "Importantly, compared to mild hypospadias, AR and CYP19A1 showed lower expressed in severe hypospadias, whereas not reaching statistical significance in our panel." (PMID 32515122, 2020).